NRP1 (neuropilin 1)
Diseases named in the same sentence as NRP1 in open-access papers (continued):
Sharing a sentence is not in itself a finding about the gene and the disease.
tumor (continued). "Nrp-1+ Treg cells have a strong potential to infiltrate tumors in a vascular endothelial growth factor (VEGF)-dependent manner and inhibit the anti-tumor immune response." (PMID 33923750, 2021). "Compared with adjacent healthy tissues, the expression levels of NRP1 and VEGF-165 were significantly increased in tumor tissues (P<0.05)." (PMID 34539883, 2021). "We found that the mRNA expression levels of FOXO3a, miR-29b-2, and miR-338 were significantly decreased in tumor tissues, whereas those of VEGF-A and NRP1 were significantly increased in tumor tissues." (PMID 33262463, 2021). "Nrp1−/− Tregs found within the TME produce IFNγ, which suppress the function of surrounding wild-type Tregs, increase anti-tumor immune activity." (PMID 33801234, 2021). "Given its widespread presence and role in tumorigenesis, NRP-1 has been the target of antitumor drugs, with peptide-based inhibition of NRP-1 leading to antiangiogenesis, and inhibition of tumor cell proliferation and migration." (PMID 33395426, 2021). "Next, we examined VEGFR1/2 and NRP1 expression and D-MVD in tumour xenografts by immunohistochemistry." (PMID 32303680, 2020). "Hence, blocking anti-NRP-1 Nbs may directly and indirectly support anti-tumor T cells." (PMID 33266104, 2020). "For instance, while SEMA3A binds specifically to NRP1 and SEMA3F binds to NRP2-containing holoreceptors to promote tumor cell normalization and inhibit metastasis in endothelial cells, SEMA3C shows similar affinities for NRP1 and NRP2." (PMID 32640719, 2020). "We verified the expression of ADARB1, ETF1, NRP1, and VPS26A in GBM tumor tissues and normal brain tissues through GEPIA." (PMID 32469390, 2020). "Comparing to the control group, in the NRP‐1 shRNA group, the number of TUNEL positive cells was significantly increased and the expression of Ki‐67 in tumours was decreased (P < .001)." (PMID 32951327, 2020). "In orthotopic implantation, the forced expression of miR-590 significantly inhibited tumour growth, and the forced expression of VEGFR1/2 and NRP1 restored the tumour growth." (PMID 32303680, 2020). "Therefore, we set out to develop NRP-1-targeting nanobodies (Nbs), as these antigen-binding moieties, derived from camelid heavy chain only antibodies, are small in size (12–15 kDa), have a strong tumor-penetrating potential and their single-domain nature allows molecular engineering." (PMID 33266104, 2020). "The qRT-PCR analyses revealed that CCA tumor tissues expressed significantly higher levels of TTN-AS1 and NRP-1 mRNA, and significantly lower levels of miR-320a, compared with adjacent normal bile duct tissues." (PMID 32801339, 2020). "NRP1 extracellular domain is necessary for EGFR-endocytosis and AKT-dependent cancer cell viability and tumor growth." (PMID 32766254, 2020). "As a proof of concept, we engineered murine MC38 colon carcinoma cells to secrete anti-NRP1 Nbs and evaluated the Nbs’ ability to modulate the tumor microenvironment (TME) and to affect tumor growth." (PMID 33266104, 2020). "Our work shows that perivascular NRP1 expression is an independent marker of improved survival in RCC patients, and reduces tumor vascularization by forming complexes in trans with VEGFR2 in the tumor endothelium." (PMID 31880322, 2020). "These embryonic bridging macrophages secrete numerous genes shared by the perivascular macrophages that drive tumor angiogenesis including the angiopoietin receptor, Tek, the VEGF co-receptor Nrp1, growth factors (Fgf2, Pgf) and MMPs (Mmp2, Mmp9)." (PMID 32484158, 2020). "Combination with in vitro and in vivo experimental results, we can conclude that miR-590 inhibits GC growth and metastasis via tumour angiogenesis and EMT pathway by targeting VEGFR1/2 and NRP1." (PMID 32303680, 2020).
tumor (continued). "In relation to the malignancy grade of the tumor, mRNA levels of SEMA3B, SEMA3C, SEMA3D, SEMA3G, PLXNA2, and CDH1 decreased while mRNA levels of SEMA3F, NRP1, ITGB3, ITGA5, and VEGFA increased with the increase of the tumor malignancy (p < 0.05)." (PMID 33036421, 2020). "We further analyzed the tumor microenvironment and observed that the pro-inflammatory MHC-IIhigh/trophic MHC-IIlow macrophage ratio was increased in tumors that produce anti-NRP-1 Nbs." (PMID 33266104, 2020). "The cleaved form of iRGD binds to NRP-1, and subsequently triggers NRP-1-dependent endocytosis, thus resulting in enhanced tumor penetration." (PMID 32847045, 2020). "As shown in human PC3 prostate cells, decreased levels of neuropilin 1, induced by NDGA treatment, lead to alterations in the motility and cell-matrix adhesion, and attenuated tumor metastasis in a nude mice model of prostate cancer." (PMID 32184727, 2020). "SEMA3C, which binds to NRP1 and NRP2 with equivalent affinity, inhibits tumor lymphangiogenesis by targeting immature vessels sprouting." (PMID 32766254, 2020). "Immunostaining and PCR analysis revealed that BTSCs highly express Sema3A and its receptors Nrp1 and PlxnA1, with expression of Nrp1 in the CD133 positive BTSCs, and absence in differentiated tumor cells." (PMID 33302912, 2020). "As the tumour colony formation assay showed, in both GBC‐SD and NOZ cells, the number of colonies was significantly lower in the NRP‐1 shRNA group (P < .01)." (PMID 32951327, 2020). "In summary, NRP1 mRNA and NRP1 protein were highly expressed in RCC, in particular in perivascular tumor cells, allowing formation of trans‐complexes with VEGFR2 expressed in the endothelium." (PMID 31880322, 2020). "Neuropilin-1 (NRP-1) is a co-receptor for semaphorins and vascular endothelial growth factor (VEGF) family members that can be expressed on cancer cells and tumor-infiltrating myeloid, endothelial and lymphoid cells." (PMID 33266104, 2020). "Sema3A has been shown to promote tumor growth by attracting NRP-1+ TAMs to the hypoxic tumor core, suppressing the activity of NRP-1+ CD8+ T cells and stimulating Treg activity." (PMID 33266104, 2020). "In colon cancer, NRP1 expression correlates with increased vessel number and poor prognosis, while NRP2 over-expression stimulates tumor progression and the down-regulation of NRP2 expression inhibits tumorigenesis and increases apoptosis." (PMID 32766254, 2020). "Although the study of NRP1 in GC remained limited, it was reported that the high expression of NRP1 due to hypomethylation was co-expressed with PDGFRB and was significantly correlated with tumor malignant phenotypes with poor prognosis." (PMID 32903845, 2020). "In summary, we show for the first time that tumor cell–expressed NRP1 forms complexes with VEGFR2 expressed by the endothelium (trans) in human RCC tumors, and halts tumor angiogenesis, thereby improving patient survival." (PMID 31880322, 2020). "NRP1 expression was analyzed in RCC tumor vessels, in perivascular tumor cells, and generally in the tumor cell compartment." (PMID 31880322, 2020). "Coexpression of the NRP1 and NRP2 genes has been reported to be significantly correlated with tumor progression through neovascularization in NSCLC41." (PMID 32678190, 2020). "If NRP1 expression decreases, TAM remain in the normoxic peripheric zones of the tumor resulting in the suppression of their pro-tumoral role." (PMID 32766254, 2020). "This appears to be especially relevant in the case of anti-tumor CD8+ T cells, in which NRP-1 limits the development of long-term memory cells." (PMID 33266104, 2020). "Previous published studies have indicated that NRP1 protein is highly expressed in human PACA tissues, and it is closely related to angiogenesis, tumor stage, and poor postoperative overall survival." (PMID 32472711, 2020). "Reduced expression of NRP1 in KRAS-transformed cells results in reduced SMAD2 phosphorylation and increased tumor growth." (PMID 30717262, 2019).
tumor (continued). "Binding of the snake venom component, rhodocetin αβ (RCαβ) to NRP1 induces the formation of a ternary complex with MET on endothelial and tumor cell membranes." (PMID 30717262, 2019). "Most of the cell-surface bound VEGF is in a signaling form, where VEGFR1-, VEGFR2-and NRP1-bound VEGF comprise 35, 17, and 29% of the total VEGF in the tumor, respectively." (PMID 31379588, 2019). "Together, Nrp-1 is required for Treg stability in the TME and facilitates interaction with other infiltrating immune cells, preventing activation of a robust anti-tumor immune response." (PMID 31681327, 2019). "Several receptors have already been explored for this approach, namely CD13, CD276, Extra domains of fibronectin (A, B), Integrin αvβ3, Neuropilin-1, Nucleolin, PDGFRβ, tissue factor, and VEGFR-2, which are overexpressed on tumor vasculature." (PMID 33568892, 2019). "To further assess mechanisms involved in the therapeutic effect of anti-Nrp-1 plus anti-PD-1 combination, we analysed CD8+ TIL from B16F10 tumours of the different groups of mice used above." (PMID 31350404, 2019). "Anti-Nrp-1 neutralising antibodies enhance the migration and cytotoxicity of Nrp-1+PD-1hi CD8+ TIL ex vivo, while in vivo immunotherapeutic blockade of Nrp-1 synergises with anti-PD-1 to enhance CD8+ T-cell proliferation, cytotoxicity and tumour control." (PMID 31350404, 2019). "Overall, these results demonstrate that anti-Nrp-1 plus anti-PD-1 in vivo treatment enhances tumour infiltration by CD8+ TIL, with increased proliferative and killing capacities, leading to strong tumour regression." (PMID 31350404, 2019). "To test tumor-inhibitory effects of siRNA-mediated knockdown of GIPC1, NRP1 and NRP2 more rigorously in an in vivo model, we subcutaneously transplanted Colo357 cells into the both flanks of immunocompromised mice." (PMID 31664117, 2019). "In the tumor microenvironment, TAMs express SEMA4D on their surface, which forms a cell-cell contact with NRP1 on Tregs and activates them and other cells, such as ECs." (PMID 30717262, 2019). "Together with plexins (plexin-A1) and neuropilins (Nrp-1 and Nrp-2), semaphorins (including SEMA3A) have the ability to interrupt vascular formation and tumor vascularization." (PMID 30971898, 2019). "Mechanistic analysis showed that electroacupuncture inhibited tumor angiogenesis by reducing the expression of vascular endothelial growth factor A (VEGF-A), its receptor VEGF-R and neuropilin 1 (NRP-1)." (PMID 31839752, 2019). "This C-type lectin-related protein binds to the b1/b2 tandem domain of NRP1 and induces the formation of a ternary complex with MET on endothelial and tumor cell membranes." (PMID 30717262, 2019). "We have also previously demonstrated that NRP-1 participates in the activation of VEGF/VEGFR2 pathway, which is crucial for tumor angiogenesis by regulating the phosphorylation of focal adhesion kinase (FAK), a key factor in cell migration and metastasis." (PMID 31572065, 2019). "We showed that the proportion of CD4+CD25+ Tregs in lymphocytes increased significantly after co-culture, and Foxp3, NRP1 and CTLA-4 expression on the surface of the cells were upregulated, indicating that the tumor cells stimulated T cell immune responses." (PMID 31417646, 2019). "In carcinoma cells, NRP1 is essential for activation of tumor growth- and invasiveness-promoting pathways involving p38MAPK, Src, and PI3K and for NRP1/Met-complex internalization." (PMID 30717262, 2019). "Results are as follows, The high expression of NRP1 in the A549RR group boosted the mRNA and protein levels of IL-17A and IL-6 in tumor tissue, respectively." (PMID 31417646, 2019). "However, whether Nrp-1 regulates tumour-specific CD8 T-cell responses is still unclear." (PMID 31350404, 2019). "Many studies on tumors have shown that Sema3A competes with VEGF for the receptor NRP-1, which inhibits VEGF-mediated angiogenesis, thereby further inhibiting the growth, invasion, and metastasis of tumor." (PMID 31467560, 2019).
tumor (continued). "In the tumor with low HSPG level, the release of PF4 shows a stronger inhibition, particularly for unbound VEGF and the VEGFR2 and NRP1 complexes (blue line)." (PMID 31379588, 2019). "Anti-Nrp-1 blocking mAb restores CD8+ T-cell effector functions and optimise suppression of tumour progression induced by anti-PD-1." (PMID 31350404, 2019). "As part of the tumor-typical desmoplasia, increased fibronectin deposition results in ECM stiffness and NRP1-knockout in CAFs impairs tumor progression." (PMID 30717262, 2019). "In contrast, NRP1 expression is induced by Wnt/β-catenin signaling in mammary stem cells and in mouse mammary tumor virus (MMTV)-Wnt1 tumor xenografts." (PMID 30717262, 2019). "Both neuropilins, i.e., neuropilin-1 (NRP1) and neuropilin-2 (NRP2), are overexpressed in various cancer types and their expressions have been correlated with tumor progression and poor prognosis." (PMID 31664117, 2019). "An immunoglobulin FC-fused tumor tissue penetrating peptide, Fc-TPP11 (HTPGNSKPTRTPRR), binds to the VEGF-binding site of NRP1 with 1000-fold higher affinity as compared to NRP2." (PMID 30717262, 2019). "NRP1 is a coreceptor with many ligands (most notably, VEGF and semaphorin), and is known to participate in tumor angiogenesis, axon guidance, tumor migration and invasion." (PMID 31586988, 2019). "In particular, we show that Nrp-1 works as a negative regulator of antitumoural activities of this CTL subset, and that blocking of this receptor in vivo strongly improves tumour regression elicited by anti-PD-1 immunotherapy." (PMID 31350404, 2019). "FK was employed to facilitate tumor penetration of the tumor antigens and JQ1 by binding with neuropilin-1 (Nrp-1), a protein overexpressed on surface of the tumor cells." (PMID 29670088, 2018). "Here, we showed that the tumor vessel density in human PDAC was reduced when NRP1 was expressed on tumor cells adjacent to blood vessels, allowing the formation of VEGFR2/NRP1 complexes in trans." (PMID 30027561, 2018). "NRP1 and KDR transcripts were detected in a majority of tumors (at least one positive biopsy core per tumor) of both GAC (6/11 and 7/11 tumors for NRP1 and KDR, respectively) and PDAC (9/11 and 8/11 tumors, respectively) in the HPA‐TMA." (PMID 30027561, 2018). "To identify VEGFR2/NRP1 complexes in human tumors, we performed antibody‐mediated in situ PLA on GAC and PDAC tumor samples." (PMID 30027561, 2018). "One such receptor is neuropilin-1 (NRP1), a co-receptor for VEGFR-2, enhancing the binding and biological activity of VEGF165, which has a wide tissue distribution that includes some tumor-derived cells and endothelial cells." (PMID 30483904, 2018). "It has been recently reported that the expression of Sema3A from tumour cells is able to promote TAM accumulation inside the tumour, particularly in the avascular areas and required neuropilin-1 (NRP-1)-signaling cascade." (PMID 29507865, 2018). "iRGD peptide is widely recognized as an efficient cell membrane penetration peptide targeting to αvβ3 integrins and neuropilin-1 (NRP-1) receptors, which show high expression in many tumor cells." (PMID 29396568, 2018). "In T241:NRP1 tumors, VEGFR2/NRP1 complexes formed both on endothelial cells (cis) and between tumor cells and endothelial cells (trans), thus creating a cis + trans condition." (PMID 30027561, 2018). "The VEGFR family includes VEGFR-1(Flt-1), VEGFR-2(KDR/Flk-1), VEGFR-3(Flt-4), NRP-1 and NRP-2 with VEGFR-2 is supposed to be closer to generation of tumor vessels." (PMID 29662638, 2018). "Neuropilin-1 (NRP-1) promotes α5β1 integrin-dependent FN1 fibril assembly and tumor growth by aiding myofibroblasts and soluble FN1 interactions." (PMID 28842594, 2017). "Diminished expression of Nrp1 in GBM cells leads to deregulation of this signaling balance, leading to VEGF-A independent angiogenesis and tumor recurrence following bevacizumab treatment." (PMID 28938007, 2017).
tumor (continued). "Bevacizumab has also been combined with MNRP1685A, a mAb against membrane-bound endothelial cell co-receptor neuropilin-1 (NRP1), overexpressed in certain tumor cells, for advanced or metastatic solid tumors (NCT00954642)." (PMID 29312320, 2017). "Deletion of Neuropilin-1 favored TAM localization in normoxic tumor regions hampering their angiogenic and immunosuppressive functions, thereby impeding tumor growth and metastasis." (PMID 28197019, 2017). "Lastly, these data showing important roles for Nrp1 signaling in GBM cells and effects on blood vessels in the tumor microenvironment have direct links to what has been reported in brain vascular development." (PMID 28938007, 2017). "To further validate this varying role of NRP1 in tumorigenesis in different cancers through in vivo studies, we utilized orthotopic human PDAC and NSCLC tumor xenografts in immunocompromised SCID mice." (PMID 29018205, 2017). "Here, we report that Neuropilin-1 (Nrp1) regulates GBM growth and invasion by balancing tumor cell responses to VEGF-A and transforming growth factor βs (TGFβs)." (PMID 28938007, 2017). "Consistently, upregulation and/or mislocalisation of NRP1 and NRP2 to the basolateral region correlates with invasiveness and poor prognosis in a number of tumour types." (PMID 28062852, 2017). "In KRASmt cells, NRP1 knockdown results in decreased SMAD2 phosphorylation and enhanced tumor growth." (PMID 29018205, 2017). "Alternatively, expression of angiogenic receptors such as NRP1 and VEGFR1 on tumor cells, in the tumor interstitial space, or in plasma can serve as biomarker candidates." (PMID 29267273, 2017). "Therefore, defective NRP-1 trafficking or degradation that result in its aberrant expression and/or membrane accumulation may potentially impact cell-membrane integrity, and hence tumor metastases." (PMID 26701889, 2016). "Here we showed that NRP-1 depletion inhibited VEGF-activated VEGF/VEGFR2 pathway, which is crucial for tumor angiogenesis by regulating the phosphorylation of FAK, a key factor in cell migration and metastasis." (PMID 26795388, 2016). "We demonstrated that NDGA suppresses NRP1 expression and consequently impairs cell motility and cell adhesion to ECM in cancer cells and attenuates tumor metastasis in nude mice model." (PMID 27863391, 2016). "The targeting specificity of TU17:MTD to tumor cells is likely to be determined by the “RPARPAR” sequence that is previously known to bind to NRP-1, a co-receptor for vascular endothelial growth factor (VEGF), expressed in tumor vessels and in most carcinomas." (PMID 27083053, 2016). "Anti-Nrp-1 not only allowed the increased expansion of tumor-derived CD4+CD8a− T cells, but it also activated tumor-derived CD4+ T cells (CD4+CD69+) in IL-10−/− and WT B16/F10 mice." (PMID 27075020, 2016). "VEGF165 and Semaphorin 3A share overlapping binding domains in the N-terminal region of the b1 domain that compete for binding to Nrp-1 and act in combination with VEGF165 to support tumor growth." (PMID 27075020, 2016). "M2 macrophages and maturing monocytes under prolonged hypoxia can produce VEGF, which is also a ligand for NRP-1 and NRP-2, and can thus promote tumor progression and angiogenesis." (PMID 26900851, 2016). "TAMs' localization to hypoxic tumor areas is controlled by the Sema3A/neuropilin-1 signaling axis, leading to plexinA1/plexinA4-dependent VEGFR1 activation and promotion of tumor growth and metastasis." (PMID 27975071, 2016). "Use of the anti-Nrp-1 antibody resulted in a significantly augmented number of CD4+TGF-β1+ Th3 cells in the TDLN and tumor tissue and tumor-derived TGF-β1-producing Treg cells from IL10−/− B16/F10 and WT B16/F10 mice." (PMID 27075020, 2016). "NRP-1 interacts with vascular endothelial growth factor (VEGF) and its receptor VEGFR2, leading to the activation of this pathway and promoting tumor angiogenesis and growth." (PMID 26795388, 2016).